IL1B (interleukin 1 beta)
Diseases named in the same sentence as IL1B in open-access papers (continued):
Sharing a sentence is not in itself a finding about the gene and the disease.
heart failure (continued). "This study showed the increased secretion of IL-1β and IL-18 when DUOX1 was overexpressed in AC16 cells, suggesting that the caspase-1-dependent pyroptosis in heart failure was triggered by the upregulation of DUOX1." (PMID 38750444, 2024). "This is attributed to the release of various cytokines, such as IL-1α, IL-1β, IL-6, and TNF-α, which negatively affect myocardial healing and contribute to the development of heart failure." (PMID 38667586, 2024). "In this context, serum levels of cytokines, including interleukin (IL)-1β and tumor necrosis factor-alpha (TNF-α), and IL-6 are elevated in HD patients, suggesting an adverse role of these substances in the pathogenesis of cardiac failure in these patients." (PMID 39070454, 2024). "In heart failure, activation of the NLRP3 inflammatory mediates the release of pro-inflammatory mediators such as IL-1β and IL-18, considered significant contributors to myocardial fibrosis and cardiac dysfunction in heart failure." (PMID 39022620, 2024). "Compared to the sham group, the model group exhibited a significant increase in the levels of heart failure biomarker NT-proBNP, as well as the pro-inflammatory cytokines TNF-α and IL-1β." (PMID 38138606, 2023). "TAC (administration for four weeks) promoted the development of heart failure, cardiac hypertrophy, and an increase in P2X7 receptor, NLRP3, and IL-1β expression in myocardial tissue." (PMID 36320147, 2022). "TAC promoted the development of heart failure, and cardiac fibrosis and increased the NLRP3, gasdermin D, ASC, cleaved caspase-1, p-NFκB, IL-1β, and IL-18 levels in myocardial tissue in mice." (PMID 36320147, 2022). "Blocking specific cytokines, such as IL1β, via monoclonal antibody targeting (Canakinumab; CANTOS trial) reduces post-MI heart failure and delivers beneficial effects in atherosclerotic disease." (PMID 35502777, 2022). "Aortic banding triggered the development of heart failure, cardiac hypertrophy, cardiomyocyte hypertrophy, and cardiac fibrosis, and increased NLRP3, NFκB, ASC, IL-1β, cleaved caspase-1 expression, and inflammatory cell infiltration." (PMID 36320147, 2022). "The hawthorn treatment group reduced the levels of IL-6, IL-8, IL-1β and TNF-α in cardiomyocytes due to doxorubicin treatment for heart failure (p < 0.01)." (PMID 36140986, 2022). "The clinical trials targeting inflammation for the treatment of heart failure, with the exception of the CANTOS trial (anti-IL-1β), have been largely disappointing." (PMID 33041853, 2020). "Activation of TLR4, caspase-1, IL-1β, and mast cells are also known to increase myocarditis and promote remodeling, fibrosis, and DCM in CVB3 myocarditis in male mice suggesting that BPA exposure could increase the risk of progression from myocarditis to DCM and heart failure in women." (PMID 31551929, 2019). "In particular, pimobendan has been shown to decrease the production of intracardiac IL-1β, IL-6, TNF-α and nitric oxide by inhibiting the activation of NFκB in mouse models of heart failure." (PMID 30935055, 2019). "The VO2 max of heart failure patients was positively related to the level of the ASC average methylation level and negatively correlated with the plasma concentration of IL-1β." (PMID 30555415, 2018). "The expressions of IL-1β, TNF-α, and IL-6 were significantly higher in MI-induced heart failure treated with hGAPDH-SiRNA than in sham." (PMID 23874864, 2013). "Furthermore, cell interaction analysis identified enrichment of interleukin-1 beta (IL-1β) and transforming growth factor beta (TGF-β) signaling in fibroblasts in heart failure." (PMID 39940764, 2025). "By using Cytoscape software (Version: 3.10.2) in conjunction with MCC algorithms of the CytoHubba plugin, we identified the top 5 hub genes within the network (IL1B, NFKB1, MAP2K1, PRKACA, and HSP90AA1), suggesting that these genes are potential targets for EMPA and MET in heart failure therapy." (PMID 40364820, 2025).
heart failure (continued). "We detected significantly lower concentrations of BNP, cTNT, and IL-1β in the serum of mice treated with dasatinib and niclosamide, further supporting the notion that senescent SARS-2-S syncytia contribute to exacerbated heart failure." (PMID 39102426, 2024). "Furthermore, MCC950 (a specific inhibitor of the NLRP3 inflammasome) prevents heart failure by suppressing NLRP3 inflammasome and IL-1β release." (PMID 38270118, 2023). "At present, some traditional Chinese medicines, such as Qiliqiangxin (QL), were reported to stabilize the gut microbiota after heart failure, inhibiting myocardial fibrosis and cardiac remodeling by reducing the generation of inflammatory factors, such as NLRP3, IL-1B, and TNF-α." (PMID 36771313, 2023). "Tumor necrosis factor (TNF) and IL-6 are well known serum biomarkers of heart failure, along with IL-1β, but IL-1β is better as a tissue biomarker rather than a serum biomarker, as its sera levels are low." (PMID 36937911, 2023). "Evidence for this hypothesis comes from previous studies that showed that circulating IL-1β levels correlate with NYHA classification and predict mortality in heart failure patients." (PMID 36741845, 2022). "In DOX-induced heart failure mice, SOD2, GPx-1, FOX3a, and SIRT3 expression are decreased, apoptotic cells and cleaved-caspase-3 expression are increased, as well as inflammatory cytokines such as IL-1β, IL-6, and TNF-α are increased." (PMID 34513812, 2021). "Previous work in this field has demonstrated an upregulation of IL-1β in heart failure patients, compared to non-failing controls, and even higher levels in deteriorating patients requiring LVAD implantation." (PMID 34768376, 2021). "As expected, we found that caspase-1 overexpression aggravated the activation of IL-1β and IL-18 in Re-TAC 4W mice, recapitulating that HP attenuates cardiac hypertrophy and regresses heart failure through downregulation of the inflammatory cascade of caspase-1." (PMID 33842546, 2021). "Synthesis of ADAMTS4 and versican in cardiac cells was induced in vitro by TNF-α and IL-1β, cytokines found in enhanced levels in the failing myocardium, suggesting inflammation as a trigger for ADAMTS-mediated versican fragmentation in heart failure." (PMID 24595230, 2014). "Furthermore, in rats with ISO-induced heart failure, pyroptosis and inflammatory responses were exacerbated, including increases in GSDMD, cleaved GSDMD, caspase 1, cleaved caspase 1, and IL-1β by 1.56- (P<0.05), 2.87- (P<0.001), 2.14- (P<0.01), 2.67- (P<0.01), and 7.11-fold (P<0.001), respectively." (PMID 36327230, 2022). "An uncontrolled production of proinflammatory mediators, such as IL-6, IL-1β, IFN-γ, and TNF-α, drives hyperinflammation during severe COVID-19 infection, leading to cardiovascular and respiratory complications, including ARDS, disseminated intravascular coagulation, and heart failure." (PMID 35955801, 2022). "In patients with heart failure, statin treatment reduces Rac1 function, NADPH oxidase activity and levels of reactive oxygen species, a finding consistent with our observation that simvastatin pretreatment reduces IL-1β/bradykinin mediated microvascular hyperpermeability." (PMID 33327440, 2020). "Visfatin increase in type-2 DM patients was related to heart failure and acute coronary syndromes; visfatin appears to mediate vascular endothelial inflammation by inducing the expression of adhesion molecules (VCAM-1 and ICAM-1) and pro-inflammatory cytokines such as IL-1β, IL-6, and TNF-α." (PMID 28590452, 2017). "However, the expressions of IL-1β and IL-6 were not different between in MI-induced heart failure treated with TLR4-SiRNA and that treated with hGAPDH-SiRNA for 2 weeks." (PMID 23874864, 2013). "Compared with a rat model of cardiac failure and miR-30b-5p-non-loaede NP groups, the expression of cardiac hypertrophy markers (ANP, BNPβ-MHC) and inflammatory factors (IL-1β, IL-6) were significantly decreased." (PMID 34658880, 2021).
pneumonia (171 papers, 2005 to 2026). An acute, acute and chronic, or chronic inflammation focally or diffusely affecting the lung parenchyma, caused by an infection in one or both of the lungs (by bacteria, viruses, fungi, or mycoplasma.). "The importance of lung IR inflammation was also demonstrated by the fact that disruption of NLRP3 inflammasome-mediated IL-1β production or sensing was associated with worse bacterial clearance as part of a superimposed pneumonia." (PMID 41467904, 2026). "Zinc deficiency can also contribute to elevated FPP levels in pneumonia because the acute-phase response, driven by proinflammatory cytokines (IL-6, IL-1β, TNF-α), triggers metallothionein synthesis and sequesters zinc in the liver and immune cells." (PMID 40615660, 2025). "IL-1β, IL-2R, and IL-8 are closely associated with pulmonary complications and disease progression in pediatric pneumonia with LC." (PMID 40406149, 2025). "Animals administrated with IV or nebulised EVs from both cell sources had lower levels of pro-inflammatory cytokines such as IL-1β and IL-8, cytokines associated with poor outcome in pneumonia patients, compared to controls." (PMID 37280647, 2023). "Pneumonia induced by K. pneumoniae or LPS is associated with the overproduction of IL-1β and neutrophil-related chemokines such as CXCL1, CXCL2, and CXCL6." (PMID 35682923, 2022). "In our study, we found S. aureus infection triggered severe pneumonia, which caused a great rise in pro-inflammatory factors, such as IL-1β, IL-6, TGF-β, MIP-2, MCP-1 and TNF-α in bronchoalveolar lavage fluid." (PMID 33255656, 2020). "For example, α-hemolysin-mediated activation of NLRP3 in a mouse pneumonia model has been linked to IL-1β-independent necrosis, pulmonary damage, and severe pneumonia." (PMID 26617605, 2015). "The treatment of these aged mice with inflammasome activators [Nigericin, which promotes potassium (K+) efflux increases the synthesis and release of inflammasome activation-dependent cytokines (IL-1β and IL-18)] increase their survival and decreases their susceptibility toward pneumonia and ALI." (PMID 32849610, 2020). "Notably, studies using mice deficient in IL-1 receptor type 1 (IL-1R1−/−) or IL-1β have shown the importance of IL-1 in conferring resistance to pneumococcal meningitis and pneumonia respectively." (PMID 21085613, 2010). "Besides the direct involvement of IL-1β causing lung damage and dysfunction, exudative fluids and the excessive accumulation of neutrophils in lung tissue also play critical roles in lung inflammation, damage, and dysfunction during pneumonia." (PMID 35682923, 2022). "The results revealed that Vb treatment significantly suppressed mRNA levels of NLRP3, Caspase-1, and IL-1β in lung tissues of RSV-infected mice with pneumonia." (PMID 41349590, 2026). "Numerous studies have shown that levels of TNF‐α, IL‐1β, and IL‐6 are significantly elevated in the serum or bronchoalveolar lavage fluid of patients with acute pneumonia or in LPS‐induced animal models." (PMID 40144560, 2025). "Other cytokines, such as IL-1β and IL-18, are also responsible for the exacerbated damage in acute pneumonia through activation of inflammasomes." (PMID 40076637, 2025). "When comparing pneumonia-affected sheep to resistant ewes, the IL-1α, IL1B, IL6, and TNF-α genes were markedly upregulated." (PMID 40711280, 2025). "For example, the serum level of IL-1β during the early stages of pneumonia correlates with disease severity." (PMID 41316271, 2025). "Within Firmicutes we recorded a selective loss of unclassified_Lachnospiraceae and Blautia, two clades whose abundance inversely correlates with IL-6/IL-1β concentration in murine pneumonia models." (PMID 41311834, 2025). "Serum inflammatory cytokine assays indicated significantly elevated levels of TNF-α, IL-1β, and IL-6 in the pneumonia group compared to the control group (p < 0.001), suggesting that pathogen infection triggered a systemic inflammatory response." (PMID 41300746, 2025).
pneumonia (continued). "The two-hit requirement in our model resembles the typical clinical ARDS-developing scenario that involves pneumonia and MV, as well as the two-signal for IL-1β production and release." (PMID 40553503, 2025). "CE reduced pro-inflammatory cytokine secretion, inhibited NLRP3, Caspase-1, and IL-1β protein expression, and upregulated key autophagy genes and proteins, thereby promoting autophagy and subsequently alleviating Hp-induced pneumonia damage in chicks." (PMID 41092609, 2025). "Intriguingly, mice that presented hypothermic reactions to secondary pneumonia had higher levels of inflammasome-related genes and higher levels of IL-1β in their lungs." (PMID 40202049, 2025). "Differential expression was noted for pyroptosis-related genes, with IL1B showing marked upregulation in pneumonia compared to normal lung samples." (PMID 39925847, 2025). "In agreement with previous reports, we confirmed that the proinflammatory cytokines IL-6, TNF-α, and IL-1β accumulated in the lungs of PmCQ2-infected mice, which is a typical response to pneumonia." (PMID 38589976, 2024). "Lung tumor necrosis factor-α, interleukin (IL)-1β, IL-6, and IL-10 were significantly decreased at 48 hours after pneumonia induction in the exercise group compared with the control group." (PMID 38193770, 2024). "Elevated IL-1β and IL-18 levels were found in the brains of mice with L. pneumophila-induced pneumonia." (PMID 39816309, 2024). "TNF-α and IL-1β are two key pro-inflammatory cytokines, the increased concentration of which often indicates the severity of pneumonia and the intensity of the inflammatory response." (PMID 37446875, 2023). "Overall, pneumonia-derived CVB4 caused significant increases in two important pro-inflammatory factors, IL-6 and IL-1b, on both sides in the early stages of infection." (PMID 37725516, 2023). "Consistent with LPS-treated mice, serum and BALF IL-1β and IL-6 levels in pneumonia patients were higher than in controls." (PMID 36923935, 2023). "In pneumonia, for instance, IL-1β and IL-18 can activate inflammatory cells, such as macrophages to release inflammatory mediators, causing inflammatory responses characterized by infiltration of macrophages and granulocytes in the lung." (PMID 36233009, 2022). "PVL exposure activates NLRP3, and binding to monocytes and macrophages leads to the release of the caspase-1-dependent pro-inflammatory cytokines IL-1β and IL-18, which induce macrophage death and exacerbate pneumonia." (PMID 35878202, 2022). "IL1RN and IL1b were also significantly upregulated interleukin genes in pneumonia cases, which were consistent with the increased expression of plasma IL-1Ra and IL-1b proteins." (PMID 36119044, 2022). "As shown from the pneumonia samples, representative proinflammatory cytokines such as IL-6, IL-1β, IL-4, IFN-γ, and TNF-α were adsorbed to the DND irrespective of the disease type." (PMID 35445003, 2022). "Compared with the model group, isorhamnetin reduced the protein expressions of SYK, IL-6, MAPK14, MAPK8, TNF-α, AKT, p-Akt, PIK3CA, EGFR and IL-1β in lung tissues of pneumonia mice." (PMID 36506534, 2022). "Activation of pro-inflammatory (M1) phenotype macrophage is a key parameter of acute pneumonia, which stimulates cytokine storm by releasing proinflammatory factors such as IL-1β, IL-6 and TNF-α." (PMID 36714100, 2022). "To further evaluate the efficiency of the phages in treating pneumonia, we examined the concentrations of cytokines, including interleukin-1β (IL-1β), IL-6, and tumor necrosis factor alpha (TNF-α), and pathological injuries at 24 and 48 h postinfection." (PMID 36165773, 2022). "The in vivo experimental results showed that rhein has a positive therapeutic effect on pneumonia, significantly reducing the concentration of pro-inflammatory factors [interleukin (IL)-6 and IL-1β] and improving lung disease." (PMID 35387347, 2022).
pneumonia (continued). "Hyperproduction of pro-inflammatory cytokines such as IL-1β, IL-6, IL-12, IFN-γ and TNF-α have been linked to the pathogenesis of tissue injury observed in SARS-CoV-2 induced pneumonia seen in humans." (PMID 34929014, 2021). "IL1B induces the synthesis of prostaglandins (PGs) that affect the pneumonia response, and PTGS2 acts as a key rate-limiting enzyme in the synthesis of PGs." (PMID 33681222, 2021). "Pathological examinations and cellular profiles of BALF showed that H-AASD exacerbated pneumonia incidence in KP infected mice and increased expression of cytokines (IL-1β, IL-6, IL-12, IFN-γ, TNF-α) and chemokines (KC, MCP-1, MIP-1α) related to KP in BALF." (PMID 34333291, 2021). "Results using a murine model of pneumonia indicate that IL-1β and IL-18 participate in the suppression of host capabilities to clear P. aeruginosa pulmonary infection." (PMID 34572625, 2021). "During the severe pneumonia it was observed that level of IL-1β was at higher concentration during fatal condition than non-fatal patients." (PMID 33634060, 2020). "Proinflammatory cytokines (TNF-α, IL-6 and IL-1β) are considered as major inducers of the inflammatory response and involved in systemic response and local injury during pneumonia." (PMID 33551807, 2020). "IL-1β leads to neutrophil activation necessary during acute phase of pneumonia, slower secretion of IL-1β increases bacterial growth resulting in faster disease progression." (PMID 33634060, 2020). "Further studies found that SFJDC had a significant immune regulatory function, reducing levels of B lymphocytes, CD8+ cells, interleukin-1α (IL-1α), IL-1β, IL-2, IgM, and IgG to improve lung function in mice with pneumonia." (PMID 32848729, 2020). "These strains caused significantly greater levels of infection in mouse models of pneumonia, decreased myeloid cell viability and promoted more IL-1β release." (PMID 33302964, 2020). "Low levels of IL-1β were only seen in 2 patients with severe pneumonia and low levels of IL-17A in 2/8 patients with severe pneumonia, and 7/14 in mild illness." (PMID 33199778, 2020). "Reduces levels of B lymphocytes, CD8+ proportion, IL-1α, IL-1β, IL-2, IgM, IgG, etc., reduces quality of thymus, spleen and lung of pneumonia mice, and increase CD4+/CD8+ and NK cell proportion." (PMID 32848729, 2020). "Hla- and IL-1β-mediated pathological injury is thought to be responsible for the high morbidity and mortality of S. aureus infection, especially pneumonia." (PMID 32793508, 2020). "It infers that superinfection with MRSA reduces expression of IL‐1β someway, and decreased expression of IL‐1β impairs the host immunity and leads to aggravated pneumonia." (PMID 32697385, 2020). "AECs or PECs or pulmonary macrophages during pneumonia secrete IL-1β that governs the ILC2s plasticity." (PMID 32849610, 2020). "In contrast to the enhanced levels of the pro-inflammatory cytokines IL-8 and TNF-α, significantly lower levels of secreted IL-1β were observed in cultures derived from patients with A-T as compared to healthy controls post-infection with S. pneumonia." (PMID 30796268, 2019). "IL-1β is a crucial inflammatory factor involved in pneumonia and research indicates that the level of IL-1β in the lungs of chronic obstructive pulmonary disease patients is higher than that of non-smokers." (PMID 31417879, 2019). "We have previously shown that production of IL-1β and other cytokines is dependent on NFκB signaling in the lung during pneumonia." (PMID 31415618, 2019). "Taken together, these data indicate that neutrophils are the primary source of P2X7R and mature IL-1β in vivo during S. pneumoniae corneal infection." (PMID 26877061, 2016). "In pneumonia, MV led to a further dramatic increase of IL-1β, IL-6 and KC, while IL-10 levels remained unaffected." (PMID 24731244, 2014).